EZH2 (enhancer of zeste 2 polycomb repressive complex 2 subunit)
Diseases named in the same sentence as EZH2 in open-access papers (continued):
Sharing a sentence is not in itself a finding about the gene and the disease.
pancreatic IPMN (1 paper, 2014). "EZH2 is associated with the accelerated cell proliferation and malignant step in pancreatic IPMN via the downregulation of p27Kip1." (PMID 25084021, 2014). "In conclusion, EZH2-mediated p27Kip1 downregulation is associated with the accelerated cell proliferation and malignant step in pancreatic IPMN." (PMID 25084021, 2014). "Here, we report that EZH2 is associated with the accelerated cell proliferation and malignant step in pancreatic IPMN via the gene silencing of p27Kip1." (PMID 25084021, 2014). "Thus, EZH2 expression in pancreatic IPMNs was associated with the high proliferative ability in malignant IPMNs due to its downregulation of p27Kip1." (PMID 25084021, 2014). "EZH2 was significantly upregulated during the malignant step from borderline atypia to CIS, suggesting that EZH2 overexpression is a late event in pancreatic IPMNs and plays an important role in the malignant step of IPMNs." (PMID 25084021, 2014). "Here, we demonstrate that EZH2 alteration promotes the acquisition of malignant potential during pancreatic IPMN progression." (PMID 25084021, 2014). "To further assess the underlying molecular mechanism of the downregulation of p27Kip1 during pancreatic IPMN progression, we focused on the alteration of EZH2 and BMI-1, which function as transcriptional repressors during tumorigenesis." (PMID 25084021, 2014). "The aim of this study is to examine the role of enhancer of zeste homologue 2 (EZH2) alteration in pancreatic IPMN progression." (PMID 25084021, 2014). "Further studies including a large population of patients with pancreatic IPMN are needed to clarify the clinical impact of EZH2 as a prognostic factor." (PMID 25084021, 2014). "Collectively, these data suggest that increased EZH2 expression during pancreatic IPMN progression may result in the transcriptional silencing of p27Kip1 and may thereby be associated with accelerated proliferative activity." (PMID 25084021, 2014).
pancreatic NETs (1 paper, 2025). "In a cell-line study of pancreatic NETs, inhibition of EZH2 led to lower cell viability and reduced proliferative activity." (PMID 40075585, 2025).
peripheral nerve injury (1 paper, 2021). Injury to a peripheral nerve. "Trimethylation of H3 lysine 27 (H3K27me3) by enhancer of zeste homolog 2 (EZH2) is an epigenetic mark that regulates inflammatory-related gene expression after peripheral nerve injury." (PMID 34020664, 2021).
pituitary tumor (1 paper, 2015). A benign or malignant neoplasm affecting the pituitary gland. "In this study, we immunohistochemically investigated the expression pattern of EZH2 in a large cohort of pituitary tumors." (PMID 26593398, 2015). "Further studies are required to unravel potential EZH2 targets in pituitary tumors and to analyze its prognostic and therapeutic impact." (PMID 26593398, 2015).
Pleural effusion (1 paper, 2013). The presence of an excessive amount of fluid in the pleural cavity. "We further examined the function of EZH2 in SUM149 cells and a new IBC cell line-FC-IBC-02 derived from pleural effusion fluid of an IBC patient." (PMID 24294976, 2013).
polyp (1 paper, 2022). A usually exophytic mass attached to the underlying tissue by a broad base or a thin stalk. "In our study, there had been an association between the high expression of MINCR and EZH2 with the type of samples (tumor and polyp) and clinical stage." (PMID 34923811, 2022). "Our results showed that EZH2 significantly increased in tumor and polyp tissues compared to the control group." (PMID 34923811, 2022).
pregnancy disorder (1 paper, 2020). A disorder that is related to pregnancy. "Similarly, EZH2 dysregulation is linked to placenta-associated pregnancy disorders." (PMID 33732505, 2020). "Similarly, EZH2 activation could repress cytotrophoblast genes, and low cytotrophoblast EZH2 expression could alter placental development and result in placenta-associated pregnancy disorders." (PMID 33732505, 2020).
Primary Sjögren’s Syndrome (1 paper, 2022). "This study aimed to characterize the role of EZH2 in the pathogenesis of primary Sjögren’s syndrome (pSS)." (PMID 35795677, 2022). "However, we did not examine the therapeutic potential of EZH2 inhibitor in the pSS model in vivo, which was a limitation of our study and warrants further study in the experimental Sjögren’s syndrome model." (PMID 35795677, 2022).
prostate neuroendocrine carcinoma (1 paper, 2021). "Detailed analysis of tumor subtypes identified CRPC and prostate neuroendocrine carcinoma as the tumors with the highest amplification rate (12–23%) of EZH2, SUZ12 and EED genes." (PMID 34202528, 2021).
respiratory infection (1 paper, 2023). "This study aimed at characterizing the function of EZH2 in AMs, which form the first defense line against various respiratory pathogens and have profound importance in the outcome of respiratory infection." (PMID 36768720, 2023).
rhabdoid soft tissue tumor (1 paper, 2021). "The diagnosis was changed to rhabdoid soft tissue tumor, which requires intensive multiagent chemotherapy, and could benefit from a selective EZH2 inhibitor." (PMID 34771600, 2021).
rhabdoid tumor of the kidney (1 paper, 2017). A rhabdoid tumor that arises from the kidney. "MRTs, as well as rhabdoid tumors of the kidney (also showing EMT), are included in the trial of tamezostat (an EZH2 inhibitor)." (PMID 28676785, 2017).
rhabdomyoma (1 paper, 2018). A benign mesenchymal tumor arising from skeletal or cardiac muscle. "SUZ12 and RbAp46 may be used as supplementary indicators together with EZH2 for differentiating RMS from rhabdomyoma." (PMID 30120321, 2018). "In this study, the expression of EZH2 protein was measured in 81 cases, 51 from RMS and 15 from fetal rhabdomyoma, as well as in 15 specimens of tumor adjacent skeletal muscle (TASM)." (PMID 30120321, 2018). "The subtype analysis showed the sensitivity and specificity of EZH2 protein in ERMS were 89.47% and 100%, respectively, which illustrated that EZH2 expression is highly sensitive and specific to ERMS and it can be utilized as a reliable marker for differentiating ERMS from rhabdomyoma." (PMID 30120321, 2018). "In conclusion, EZH2 was highly expressed in LMS and RMS and it may be utilized as a new marker for differentiating well–differentiated LMS from cellular leiomyoma, or ERMS from rhabdomyoma." (PMID 30120321, 2018). "EZH2 protein expression was detected in 36 of 51 (70.58%) RMS, but not in rhabdomyoma and TASM (p < 0.05)." (PMID 30120321, 2018). "In this study, EZH2 protein expression was detected in 70.58% of RMS, but none was found in rhabdomyoma and TASM." (PMID 30120321, 2018).
Right ventricular hypertrophy (1 paper, 2012). In this case the right ventricle is more muscular than normal, causing a characteristic boot-shaped (coeur-en-sabot) appearance as seen on anterior- posterior chest x-rays. "EZH2 protein expression in mouse PASMCs were correlated with an increase in right ventricular systolic pressure and Right Ventricular Hypertrophy (RVH)." (PMID 22662197, 2012).
salivary duct carcinoma (1 paper, 2021). An aggressive, high grade adenocarcinoma that arises from the salivary glands. "The association between EZH2 or H3K27me3 expression and clinical outcomes in patients with salivary duct carcinoma treated with AR- or HER2-targeted therapy." (PMID 35186711, 2021). "The association between EZH2 or H3K27me3 expression and clinical outcomes in patients with salivary duct carcinoma treated with conventional therapy." (PMID 35186711, 2021).
sarcopenia (1 paper, 2022). Progressive decline in muscle mass due to aging which results in decreased functional capacity of muscles. "The sarcopenia‐associated dmCpGs were enriched within EZH2 target genes and sites of H3K27 trimethylation." (PMID 34862756, 2022). "Moreover, examination of the chromatin landscape of the sarcopenia‐associated dmCpGs found that they were localized to EZH2 target genes and regions of H3K27 trimethylation." (PMID 34862756, 2022). "There was also an over‐representation of the sarcopenia, ALMi, grip strength, and gait speed‐associated dmCpGs with sites of H3K27 trimethylation (all P ≤ 0.05) and amongst EZH2 target genes (all P ≤ 0.05)." (PMID 34862756, 2022). "Although in sarcopenia, there was both hypermethylation and hypomethylation of the dmCpGs enriched in EZH2 target genes, suggesting epigenetic dysregulation of the EZH2 pathway in sarcopenia, rather than over‐activity or under‐activity of the EZH2 pathway." (PMID 34862756, 2022).
schistosomiasis (1 paper, 2023). An infectious disease caused by parasitic trematodes of the genus Schistosoma that colonize human blood vessels and release eggs that can cause granulomatous reactions leading to acute (swimmer's itch or acute schistosomiasis syndrome) or chronic disease. "This ultimately led to the identification of H3K27me3 methyltransferases G9a (KMT1C, EHMT2) and EZH2 (KMT6) inhibitors as development-arresting compounds and potential drugs to treat schistosomiasis." (PMID 37981859, 2023).
serous ovarian tumor (1 paper, 2014). "This study showed that serous ovarian tumor cells express EZH2 and increasing EZH2 expression is associated with increasing malignant grade of serous ovarian tumor." (PMID 25025074, 2014). "Both tumor cells and cancer-associated fibroblasts express EZH2 which then contributes to the malignant grade of serous ovarian tumor." (PMID 25025074, 2014). "Because EZH2 expression is important in many kinds of cancer stem cells, we detected EZH2 expression in PGCCs and examined its association with the malignant grade of human serous ovarian tumor." (PMID 25025074, 2014). "EZH2 protein is also expressed in the CAF and shows a tendency to increase expression as malignancy increases in serous ovarian tumors." (PMID 25025074, 2014).
sinonasal carcinoma (1 paper, 2024). "EZH2 inhibitors are promising therapeutic candidates for SMARCB1-deficient sinonasal carcinoma." (PMID 38836164, 2024).
skin sarcoma (1 paper, 2021). A sarcoma that arises from the skin. "Due to the role of EZH2 in skin sarcomas, tazemetostat may be effective against these cancers." (PMID 35008848, 2021).
squamous cervical intraepithelial lesions (1 paper, 2013). "Another PcG protein, EZH2, was also recently shown to be up-regulated in high grade squamous cervical intraepithelial lesions (HSILs) compared to normal cervical epithelium, further implicating chromatin remodeling changes in tumor initiation and progression." (PMID 23592995, 2013).
testicular teratoma (1 paper, 2018). "Our results suggested that the expression of a cell cycle gene, Ccnd1, was upregulated by Dnd1 deficiency via the loss of Ezh2 expression and of H3K27me3 in Dnd1ter/ter testicular germ cells, and this molecular pathway may play a role in testicular teratoma development in Dnd1ter/ter testes." (PMID 29378702, 2018).
testicular tumor (1 paper, 2019). "Gonadotropin-releasing hormone treatment may protect against testicular tumor development by downregulating oncogenes, such as MALAT1, mTOR, C-MYC, and EZH2 to enable normal germ cell development." (PMID 31890219, 2019).
thoracic tumors (1 paper, 2025). "Additionally, targeted therapies involving Enhancer of Zeste Homolog 2 (EZH2) inhibitors and histone deacetylase (HDAC) inhibitors have shown promising therapeutic potential in SMARCA4-deficient undifferentiated thoracic tumors." (PMID 41312169, 2025).
tubular carcinoma (1 paper, 2016). "Low grade tubular carcinoma with well formed tubules and mild nuclear atypia showed a low level of EZH2 expression with only scattered positive cells." (PMID 27113214, 2016).
uremia (1 paper, 2022). A clinical syndrome associated with the retention of renal waste products or uremic toxins in the blood. "The expression of EZH2 in endothelial cells was also increased after uremia toxin stimulation." (PMID 35906216, 2022).
urinary tract infection (1 paper, 2016). "In our ongoing and future studies, we hope to delineate the factors from EV derived from both infected and uninfected cells that regulate EZH2 and the pathobiology of urinary tract infection." (PMID 26964089, 2016). "Direct relationships amongst WNT expression and signaling, EZH2 and urinary tract infection-induced proliferation remains an exciting area to be explored in greater depth." (PMID 26964089, 2016).
uterine carcinosarcoma (1 paper, 2023). A usually aggressive malignant neoplasm arising from the uterine corpus and less often the cervix.
uterine diseases (1 paper, 2020). "Conditional loss of EZH2 in the uterus upregulated genes associated with uterine diseases, including keratin 5 (Krt5), keratin 15 (Krt15), the maternally-imprinted gene- H19, leucine-rich repeat-containing G-protein-coupled receptor 5 (Lgr5), and cell division cycle associated 5 (Cdca5)." (PMID 33732505, 2020). "Lastly, we will consider the role of EZH2 in uterine diseases." (PMID 33732505, 2020).
uterine sarcoma (1 paper, 2025). "Our research team is the first to introduce a combination of EZH2 inhibitors and histone deacetylase inhibitors as a potential epigenetic therapy for uterine sarcoma." (PMID 40464712, 2025). "This study aimed to assess the effect of single and combination treatments using HDAC and EZH2 inhibitors on human uterine sarcoma cells under both 2D and 3D culture conditions." (PMID 40464712, 2025). "This study aimed to assess the effect of dual targeting of EZH2 and HDACs on the phenotype of uterine sarcoma cells in both 2D and 3D culture systems." (PMID 40464712, 2025).
uterine tumors (1 paper, 2014). "As an exception, short exposure of Eker rats to GEN at PND 10–12 inactivated the HMT EZH2 by phosphorylation, leading to reduced levels of repressive H3K27me3 levels and promotion of benign uterine tumors." (PMID 25322458, 2014).
xerostomia (1 paper, 2022). Dryness of the mouth resulting from reduced salivary secretion. "We also examined the EZH2 expression in the salivary gland from pSS and non-SS xerostomia controls using immunohistochemistry, which revealed that EZH2 was expressed in salivary gland epithelial cells from pSS and non-SS xerostomia controls as well as in lymphocytes from pSS." (PMID 35795677, 2022).
ZIKV infection (1 paper, 2025). "The increased expression of EZH2 transcripts and H3K27me3 methylation levels at the initial phase of ZIKV infection of mosquito cells further supports the observation noted with DZNep treatment." (PMID 39946368, 2025). "In addition, increased EZH2 histone methyl transferase-like gene transcripts and methylated histone (H3K27me3) levels were evident in mosquito cells upon ZIKV infection." (PMID 39946368, 2025). "In addition, up-regulation of EZH2 transcripts at the initial phase of ZIKV infection could facilitate increased transfer of methyl groups from SAMe to enhance H3K27me3." (PMID 39946368, 2025).
tumor (2,280 papers, 2005 to 2026). "Considering the association between EZH2 and immunosuppressive tumor microenvironments, we administered crotonate to immunocompetent mice for further investigation." (PMID 41544165, 2026). "Further investigation into methylation patterns at specific CpG sites within the EZH2 promoter, cg08558971 and cg18416251, revealed distinct and inverse methylation profiles at different tumor stages, each significantly linked to overall survival." (PMID 41209556, 2025). "In several cancers, including melanoma, head and neck, and prostate tumors, EZH2 inhibition is associated with increased tumor immunogenicity and enhanced responsiveness to CTLA-4 or PD-1/PD-L1 blockade." (PMID 41463268, 2025). "Tazemetostat shows increased activity in tumors lacking integrase interactor 1 (INI1, also known as SMARCB1), as INI1 loss allows EZH2 to act as an oncogenic driver in tumor cells." (PMID 40076599, 2025). "Overexpression of the epigenetic regulator EZH2 has been linked to tumour initiation, metastasis, and poor prognostic outcomes through its expansion of pro-tumour cells." (PMID 41463341, 2025). "The significant epigenetic and transcriptomic alterations caused by EZH2 in both tumor and immune cells play a key role in shaping the immune-suppressive activity of solid tumors." (PMID 41226368, 2025). "A heatmap was generated to visualize the clustering patterns and methylation levels of EZH2-associated CpG sites in tumor samples." (PMID 41209556, 2025). "The observed down-regulation of microRNAs and up-regulation of EZH2 mRNA in various cancers is associated with clinical features such as pathological grading and tumor staging." (PMID 40028035, 2025). "This chromosomal deletion causes the haploinsufficiency of several key tumor suppressors located on chromosome 7, such as EZH2, PMS2, HUS1, and NAMPT." (PMID 40981111, 2025). "PD-L1 immunoexpression was associated with better survival outcomes in ECs, while EZH2 overexpression was correlated with higher tumour grade and aggressive histological subtypes." (PMID 40310411, 2025). "The high expression of HOTAIR and EZH2 has been associated with tumor progression and poor prognosis." (PMID 41353219, 2025). "Immunohistochemical staining for H3K27me3 showed retained nuclear expression in tumor cells, consistent with the activity of the EZH2 Y646F mutation." (PMID 40664798, 2025). "Overexpression or mutation of EZH2 has been associated with tumor progression and metastasis across several cancers." (PMID 40872531, 2025). "Elevated EZH2 expression is often associated with aggressive tumour behaviour and poor prognostic outcomes in a myriad of malignancies, including ECs." (PMID 40310411, 2025). "Given the importance of EZH2 in directing tumor growth and metastasis, we next assessed the tumorigenicity of EZH2 variants." (PMID 39850359, 2025). "Preclinical studies have shown that EZH2 inhibition suppresses tumor growth, particularly in PM harboring BAP1 loss." (PMID 41463268, 2025). "Activation of KDR enhances tumor angiogenesis and growth by upregulating oncogenic factors such as Enhancer of Zeste Homolog 2 (EZH2), which is associated with increased cell proliferation and migration." (PMID 38260532, 2025). "These intrinsic events within tumor cells enhance ER stress‐associated ubiquitylation and degradation of the EZH2/MYC axis by triggering the UBA6‐UBE2Z‐FBXW7 ubiquitin cascade." (PMID 39823459, 2025). "Given that somatic EZH2 variants are implicated in various cancers, particularly hematological malignancies, tumor surveillance is an important consideration." (PMID 40922349, 2025). "Another promising EZH2 inhibitor, GSK343, also selectively inhibits H3K27 methylation and has shown efficacy in reactivating silenced tumor-suppressor genes, particularly in cancers with EZH2 mutations or overexpression." (PMID 41335282, 2025).